ERBB2 (erb-b2 receptor tyrosine kinase 2)
Diseases named in the same sentence as ERBB2 in open-access papers (continued):
Sharing a sentence is not in itself a finding about the gene and the disease.
breast cancer (continued). "The ablation of CDK4 using siRNA in erbB2-induced mammary tumor cells eliminates their oncogenic properties." (PMID 26528855, 2015). "ERBB2 (HER2) staining can also show clonal variation in breast carcinomas and this is more pronounced in gastric adenocarcinomas with variation in both HER2 protein expression and gene amplification occurring across a single tumour." (PMID 26101870, 2015). "Intrinsic sub-typing of breast carcinomas based on global gene expression profiles has revealed large differences between the basal-like, ERBB2/Her2Neu and luminal subtypes regarding patterns of CNA's." (PMID 26553136, 2015). "Disruption of Ptk6 significantly delayed and reduced ERBB2-induced mammary gland tumor formation and metastasis, providing strong rationale for therapeutically targeting PTK6 alone or in combination with other agents in ERBB2/HER2-positive breast cancers." (PMID 26247733, 2015). "The prognosis of breast carcinoma is mostly influenced by tumor stage, grade, overexpression of v-erb-b2 avian erythroblastic leukemia viral oncogene homolog 2 (ERBB2), and hormonal receptors." (PMID 26226484, 2015). "Gab2 and ErbB2 are co-amplified in a subset of breast carcinoma, and co-expression of Gab2 with ErbB2 results in an invasive phenotype, and increases proliferation of MCF-10A mammary cells in a three-dimensional culture." (PMID 26095858, 2015). "Mice lacking cyclin D1 were refractory to mammary tumor development induced by the ErbB2 oncogene, the ortholog of HER2, which is frequently overexpressed in human breast carcinomas." (PMID 26528855, 2015). "This especially holds true in ErbB2-positive human breast cancer cells, which have a high degree of fat storage." (PMID 25229978, 2014). "A dual, reversible EGFR/ErbB2 inhibitor, lapatinib (Tykerb) in particular has demonstrated significant activity in ErbB2-positive breast cancers and now is approved to be used in this indication." (PMID 25238247, 2014). "In a breast cancer cell line overexpressing ErbB2, embelin alone decreased the viability of cells (tetrazolium), although siRNA to XIAP did not." (PMID 24603802, 2014). "Our previously published work showed that a constitutively active Pparγ1 mutant (PγCA) collaborated with oncogenic ErbB2 to promote mammary tumor growth." (PMID 25229978, 2014). "In view of these facts, experiments were designed to investigate the plasma membrane proteome of a variety of human breast cancer cell lines representing hormone-responsive, ErbB2 over-expressing and triple negative cell types, as well as a benign control." (PMID 25029196, 2014). "In humans, ERBB2/HER2 is commonly amplified in breast cancer, leading to receptor over expression and driving the activation of downstream pathways that stimulate malignant cell proliferation." (PMID 25269082, 2014). "As shown in Fig4B, a breast cancer cohort (GSE25066) with a lower percentage of Luminal-B and ERBB2+ breast cancers would show a better DFS for Epi breast cancers." (PMID 25214461, 2014). "ERBB2 is overexpressed in HER2 positive breast cancers whereas basal epithelial-like (basal-like) tumors are ER negative (ER-)." (PMID 25134718, 2014). "These include gene silencing through aberrant hypermethylation (e.g. IGFBP3) and affect genes characterizing breast cancer sub-types (e.g. ERBB2)." (PMID 25071007, 2014). "The benefits of dual targeting of ErbB2 in breast cancer have been recognized and recently dual targeting has been accepted as an additional treatment strategy." (PMID 24709902, 2014). "The expression of VRK1 and VRK2 as well as estrogen receptor and ERBB2 were determined in a panel of eight human breast cancer cell lines, including four of each type, luminal or basal." (PMID 24731990, 2014). "It is interesting to note that a study addressing the impact of Cd151 deletion in another mouse model of breast cancer (the ErbB2 model) has recently been published by Deng and colleagues." (PMID 25012362, 2014).
breast cancer (continued). "Although ErbB2 targeted therapies represent a significant advancement in the treatment of aggressive breast cancers, their clinical efficacy has been limited by the inevitable development of therapeutic resistance, particularly in the advanced stage setting." (PMID 24551203, 2014). "Upon photo-activation, 7-methylpyridopsoralen significantly inhibited the growth and viability of ErbB2+ breast cancer cells, which correlated with inhibition of phosphorylated and total ErbB2 protein expression." (PMID 24551203, 2014). "The TweakR distribution in term of staining intensity, percentage of positive tumor cells, and H-score is detailed among the overall studied population and among the 3 main breast cancer sub-groups, i.e. luminal, ERBB2, and triple negative tumors." (PMID 25375638, 2014). "FASN expression has been reported to be regulated by the human epidermal growth factor receptor HER2 oncogene (erbB2) through phosphatidylinositol 3-kinase (PI3-K)/Akt in breast cancers as well as by mTOR signaling pathways in colorectal cancer cells." (PMID 25255125, 2014). "Further supporting our claim is work from another group showing that the receptor tyrosine kinase ErbB2/HER2 is a direct substrate of PTPRO, and low levels of PTPRO expression correlated with reduced survival of HER2-positive breast cancer patients." (PMID 24919593, 2014). "Breast cancer subtypes are defined using the expression levels of key genes such as estrogen receptor (ER), progesterone receptor (PR), and erbB-2 (HER-2/neu)." (PMID 25080362, 2014). "Supportively, both CTSB and CTSL1 mRNA and their protein levels also correlate positively with ErbB2 status in primary breast cancer." (PMID 24709902, 2014). "Overexpression of the epidermal growth factor receptor 2 (ErbB2) occurs in approximately 25% of all breast cancers and is correlated with disease progression, decreased survival and metastasis." (PMID 25606587, 2014). "Human epidermal growth factor receptor -2 (Her2-neu/ ErbB2) is a membrane tyrosine kinase and oncogene that is overexpressed and gene amplified in about 20% of breast cancers." (PMID 24428917, 2014). "ERBB2-targeted mAb induces apoptosis by reducing Bcl-2 or Mcl-1 expression in ERBB2-amplified breast cancer cells." (PMID 24970817, 2014). "Independent of ICL formation, the antitumor effects of PUVA in ErbB2+ breast cancer models can instead be mediated through inhibition of ErbB2 activation and signaling." (PMID 24551203, 2014). "We therefore chose the Tg(MMTV-erbB2) mouse model, where breast cancers arise spontaneously due to transgenic erbB2-overexpression." (PMID 23963762, 2014). "We reported that the specific class I HDAC inhibitor entinostat (also known as MS-275 or SNDX-275, Syndax Pharmaceuticals, Inc., Waltham, MA) selectively downregulated erbB2/erbB3 receptors and induced apoptosis in erbB2+ breast cancer cells." (PMID 24886126, 2014). "All the same kinases were also found central for the invasiveness of the ErbB2 positive MDA-MB-453 and SK-BR-3 breast cancer cells endogenously expressing high levels of the full length ErbB2." (PMID 24709902, 2014). "Along with the biological impact of ERBB3 signaling on ERBB2-amplified breast cancer, active ERBB3 is a means of escape from therapeutic suppression by several tyrosine kinase inhibitors." (PMID 25248370, 2014). "The effect of miR-17/20 was next assessed in the NAFA cell line which was derived from an ErbB2-induced mouse mammary tumor." (PMID 24658544, 2014). "Here, we present a study on ErbB2+ mammary cancer through the synergistic union of wet-lab experiments and applied mathematical techniques." (PMID 25184361, 2014). "Here, we present a model describing the initial phase of ErbB2+ mammary cancer progression, which arises from a joint effort combing mathematical modeling and cancer biology." (PMID 25184361, 2014). "Expression of LDH depends on HSF1, which binds to the LDHA gene promoter in human breast cancer cells overexpressing ERBB2." (PMID 24467529, 2014).
breast cancer (continued). "Cross-talk between ER and erbB2 or EGFR signaling promotes hormone-independent growth of breast cancer cells." (PMID 24886126, 2014). "Treatment of ErbB2+ breast cancer cells with the combination of 8-MOP, UVA irradiation, and neratinib, each at sub-lethal doses when used alone, resulted in significantly enhanced inhibition of cell viability." (PMID 24551203, 2014). "Focal adhesion kinase (FAK) has an important role in the invasion promoting cytoskeleton remodeling induced by ErbB2 and TGFβ in breast cancer cells." (PMID 24709902, 2014). "When we examined the effects of adding targeted therapies, including HDAC and PI3K inhibitors, to PUVA therapy, we found that neratinib, at sub-lethal doses alone, significantly increased apoptosis in ErbB2+ breast cancer cells when combined with PUVA." (PMID 24551203, 2014). "Over the last 15 years, the humanized monoclonal erbB2/HER2 antibody trastuzumab (Herceptin) has been successfully used for clinical treatment of patients with HER2-positive breast cancers." (PMID 24571711, 2014). "In the current study, we investigated the role of Pparγ K154/155 acetylation on lipid production in ErbB2-positive breast cancer cells." (PMID 25229978, 2014). "We showed that specific knockdown of erbB3 by a siRNA abrogated erbB2-mediated tamoxifen resistance in breast cancer cells via enhanced apoptosis." (PMID 24886126, 2014). "p130Cas/BCAR1 cooperates with ErbB2 not only in mammary cell transformation but also in driving breast cancer cell migration and invasion and formation of metastasis." (PMID 25606587, 2014). "MM-121 significantly enhanced trastuzumab-induced growth inhibition in erbB2+ breast cancer cell lines, and was able to overcome trastuzumab resistance." (PMID 24886126, 2014). "Such normalisation is required for detection of amplification or deletion in disease states, such as ERBB2 amplification in breast cancer." (PMID 24853859, 2014). "HER2/ERBB2 is primary known as being amplified and activated in breast cancer causing high recurrence rates and increased mortality in approximately 15% of all patients." (PMID 24879454, 2014). "ErbB3 serves as a critical co-receptor of erbB2, and its expression is a rate-limiting factor for erbB2-induced breast cancer cell survival and proliferation." (PMID 24886126, 2014). "In concurrence with its relevance to EMT, the luminal types express higher level of the miR-200 family than ErbB2 overexpressing and basal-like breast cancer." (PMID 25216122, 2014). "For example, ErbB2 upregulation promotes breast tumorigenesis and treatments aiming at blocking ErbB2 function have remained an effective therapy against human breast cancer." (PMID 24718286, 2014). "Approximately 20–25% of breast cancers overexpress the human epidermal growth factor receptor-2 (HER2 or ErbB2)." (PMID 25538891, 2014). "Instead, the viability of lapatinib resistant ErbB2+ breast cancer cells is dependent upon other factors." (PMID 24551203, 2014). "Consistent with an important role of ERBB2 in breast cancer metastasis, overexpression of a constitutively activated form of ERBB2 (i.e. NeuT) in mice is sufficient to trigger metastatic mammary tumors." (PMID 24937171, 2014). "Module 7 (7-ERBB2), the ERBB2 signaling module, contains only 4 genes and is essentially a minimal ERBB2 amplicon in Her2+ breast cancer." (PMID 24516633, 2014). "Together, these results suggest that the conserved lysyl residues K154/K155 of Pparγ1 are acetylated and play an important role in lipid synthesis in ErbB2-positive breast cancer cells." (PMID 25229978, 2014). "We discuss these issues using data from SNP arrays, whole exome sequencing and pathologist purity estimates on several breast cancers characterized by ERBB2 amplification." (PMID 25270265, 2014). "There are three major types of breast cancer based on the expression of estrogen and progesterone receptors and ERBB2, a member of the EGF receptor family." (PMID 24731990, 2014).
breast cancer (continued). "There is also data to suggest the involvement of AXL activation in lapatinib-resistance in ErbB2 positive breast cancer." (PMID 25238247, 2014). "In contrast, co-expression of erbB2 and erbB3 is a common event in breast cancers and breast cancer-derived cell lines." (PMID 24886126, 2014). "Pertuzumab, a humanized monoclonal antibody that also targets the NH2-terminal domain of ErbB2 and blocks the ErbB2 dimerization with ErbB3, is recently also accepted for a treatment of ErbB2 positive breast cancer in combination with chemotherapy." (PMID 24709902, 2014). "So PHLDA1 can fine-tune the overall output of ErbB2 signaling in ErbB2 dependent lung and breast cancer cells." (PMID 25238247, 2014). "Even though Luminal-B and ERBB2+ breast cancer subtypes are of the Epi type (Blicket al, 2008) (Fig2B), they have poor OS and DFS, similar to that of the Mes type, triple-negative breast cancers (Prat & Perou, 2011; Ishitobiet al, 2013)." (PMID 25214461, 2014). "We also found that treatment of erbB2+ breast cancer cell lines refractory to trastuzumab with MM-121 resulted in a dramatic inhibition of PI-3 K/Akt signaling." (PMID 24886126, 2014). "Acquired resistance has also been developed to the anti-erbB2 monoclonal antibody Trastuzumab (Herceptin®) in HER2+ breast cancer patients, which seems to be mediated by IGF-1R." (PMID 24709958, 2014). "Several expression array analyses have been carried out in order to identify the genetic signature activated by ErbB2 that defines the malignancy of ErbB2 in breast cancer." (PMID 24709902, 2014). "Expression of p85ErbB2 driven by a heterologous promoter renders ErbB2+ breast cancer cells that are normally sensitive to the antitumor effects of lapatinib, resistant to lapatinib and other ErbB2 targeted therapies." (PMID 24551203, 2014). "Overexpression of ErbB1, ErbB2, and ErbB3 in transgenic mouse models contributes to mammary tumor formation." (PMID 25516216, 2014). "Knocking out phosphatase and tensing homolog (PTEN), which is a tumor suppressor that is inactivated in 40% or ErbB2-positive breast cancers, increases angiogenesis and metastasis from ErbB2 overexpressing mammary gland." (PMID 24709902, 2014). "In breast cancer, previous cluster analysis of gene expression data has identified several different subtypes including luminal (A and B), ErbB2 over-expressing and basal-like breast cancer." (PMID 25216122, 2014). "For example, patients who experienced basal-like or ERBB2+ breast cancer have a worse prognosis compared to those that were identified with luminal A or normal-like breast tumors." (PMID 25076125, 2014). "Here we are interested in the ‘HER2-positive’ subtype of breast cancer, overexpressing the human epidermal growth factor receptor 2 (HER2, also termed ErbB-2)." (PMID 24970389, 2014). "Overexpression of the ERBB2 gene, which encodes the oncoprotein HER2, occurs in 20 to 25% of human breast cancers and is associated with poor prognosis." (PMID 24571711, 2014). "Our recent studies using both mouse and human mammary/breast cancer cell models indicate that the existence of erbB3 is required to maintain erbB2’s tyrosine kinase activity." (PMID 24886126, 2014). "The growth and viability of ErbB2+ breast cancer cell lines was significantly inhibited by PUVA therapy in a dose-dependent manner." (PMID 24551203, 2014). "ErbB2 amplification is most common in breast cancer and concerns about 25%–30% of invasive ductal breast carcinomas." (PMID 24709902, 2014). "Loss of expression or function of several signaling molecules inhibits lung metastasis of mammary tumors in ErbB2/Neu overexpressing mice." (PMID 24709902, 2014). "We have previously shown that active Pparγ promotes ErbB2-positive breast cancer growth through enhanced angiogenesis." (PMID 25229978, 2014).